SNORD114-29 (small nucleolar RNA, C/D box 114-29)
Synonyms: 14q(II-29)
Gene: Small nucleolar RNA gene on chromosome 14 (100,990,091 to 100,990,160, forward strand). Ensembl gene ENSG00000201689.
Gene Ontology:
Biological process: RNA processing
Cellular component: nucleolus
Homologues: Orthologues: macaque SNORD114-29 (90% identical). Paralogues in human: SNORD114-20 (94% identical), SNORD114-23 (91% identical), SNORD114-25 (87% identical), SNORD114-28 (87% identical), SNORD114-15 (86% identical), SNORD114-22 (86% identical), SNORD114-26 (86% identical), SNORD114-5 (86% identical), SNORD114-9 (86% identical), SNORD114-21 (84% identical), SNORD114-1 (81% identical), SNORD114-18 (81% identical), and 26 more.